STAT3 (signal transducer and activator of transcription 3)
Diseases named in the same sentence as STAT3 in open-access papers (continued):
Sharing a sentence is not in itself a finding about the gene and the disease.
colorectal cancer (continued). "Importantly, phosphorylated STAT3 has been shown to bind to the Nanog promoter and regulate its transcription in liver CSCs and colorectal cancer (CRC) cells 44-46." (PMID 31534499, 2019). "The Janus kinase (JAK) inhibitors could inhibit tumor growth in gastric and colorectal cancer via suppressing the IL-6/JAK2/signal transducer and activator of transcription 3 (STAT3) pathway and enhancing the secretion of anti-tumor cytokines." (PMID 30658426, 2019). "Furthermore, a phase III trial of Napabucasin for refractory colorectal cancer highlighted STAT3 as an essential target for the treatment of patients with elevated pSTAT3 expression." (PMID 31277685, 2019). "Additionally, the expression of STAT3 and mTOR was analyzed in paired colorectal cancer and normal tissues collected from clinical patients." (PMID 31287013, 2019). "To further determine whether exosomal p-STAT3 can induce 5-FU resistance in colorectal cancer in vivo, we established a subcutaneous xenograft model in BALB/c nude mice with RKO/P cells." (PMID 31324203, 2019). "Furthermore, we characterized STAT3 signalling in the CAC model mice, which was reportedly associated with colorectal cancer." (PMID 30905249, 2019). "Moreover, another recent report shows that blocking KRAS-dependent ERK1/2 signaling in colorectal cancers activates JAK/STAT3 signaling." (PMID 30777101, 2019). "Interestingly, p-JAK2 and p-STAT3 were found to be remarkably enhanced in COX2 (cyclooxygenase-2) overexpressing colorectal cancer cells." (PMID 30987378, 2019). "In addition, in colorectal cancer, TAMs-derived IL-6 activates the STAT3 pathway, and activated STAT3 transcriptionally blocks the tumor suppressor miR-204-5p expression." (PMID 31629410, 2019). "However, miR-4500 inhibitor decreased cytotoxicity, colony formation, PARP cleavage, and p-STAT3 induced by ursolic acid in colorectal cancer cells." (PMID 30597956, 2018). "In this study, we wished to determine whether transcription factor STAT3 bound to hTERT promoter region in colorectal cancer cell lines." (PMID 30250641, 2018). "Interestingly, the STAT3 pathway has previously been reported to be critical for colorectal cancer cell growth promoted via EGFR18." (PMID 30410004, 2018). "We will pursue the STAT3-telomerase-cancer stem cell axis in colorectal cancer in the next phase." (PMID 30250641, 2018). "Studies have shown that activation of STAT3 pathways lead to the transcription of target genes necessary for cellular proliferation, and aberrant STAT3 activation has been found in many solid malignancies, including colorectal cancer." (PMID 29963254, 2018). "Collectively, these results reveal that the IL-6 secreted by CC-MSCs enhances the progression of colorectal cancer cells through IL-6/JAK2/STAT3 signaling, and could provide a novel therapeutic or preventive target." (PMID 29348540, 2018). "STAT3 is involved in immune response and aberrantly expressed in colorectal cancer cells." (PMID 30250641, 2018). "JAK2 and STAT3 activation have an important effect on metastasis in colorectal cancer." (PMID 29348540, 2018). "Colorectal cancer cells express constitutively active STAT3." (PMID 30190788, 2018). "miR-34a is a regulator of IL-6/STAT3 signaling in colorectal cancer." (PMID 28441730, 2017). "Similarly, it has been demonstrated that the TFF3- and VEGF-stimulated invasion and growth of colorectal cancer cells is dependent on STAT3 activation." (PMID 29100386, 2017). "Furthermore, miR-34a can suppress tumor progression by inhibiting the IL-6R/STAT3/miR-34a feedback loop and by inhibiting IL-6-induced colorectal cancer cell EMT, invasiveness, and metastasis." (PMID 28441730, 2017).
colorectal cancer (continued). "Indeed, many reports showed that constitutive activation of STAT3 is frequently detected in primary human colorectal carcinoma and contributes to invasion, survival, and growth of colorectal cancer cells." (PMID 28870287, 2017). "Moreover, activation of oncogenic transcription factors, such as signal transducer and activator of transcription 3 (STAT3), induces colorectal carcinoma." (PMID 29245972, 2017). "Additionally, the relationship of p-STAT3 overexpression with clinicopathological parameters of colorectal cancer was investigated." (PMID 27504822, 2016). "Therefore, a systematic review and meta-analysis were conducted to explore the relationship between p-STAT3 expression and clinicopathological parameters, as well as the overall survival of colorectal cancer patients." (PMID 27504822, 2016). "Interestingly, a non-canonical function of STAT3 in mitochondria has been proposed to mediate STAT3-dependent resistance of colorectal cancer cells to apoptosis by decreased production of reactive oxygen species." (PMID 26938566, 2016). "However, the prognostic value and clinicopathological parameters of p-STAT3 expression in colorectal cancer were undefined." (PMID 27504822, 2016). "Thus, the potential publication bias was assessed between p-STAT3 expression and lymph node metastasis by funnel plot, Egger test and Begg test in colorectal cancer." (PMID 27504822, 2016). "We then examined specimens from 150 colorectal cancer patients and showed an increase in phosphorylation at S727 of STAT3 and Col17a1 expression in correspondence with tumour stages, and the expression of these two markers inversely correlated with patient survival." (PMID 27306323, 2016). "Besides, in previous meta-analysis papers, we searched 2 studies which involved colorectal cancer and p-STAT3." (PMID 27504822, 2016). "Activation of STAT3 in colorectal cancer patients increases β-catenin transcription activity." (PMID 27036017, 2016). "STAT3 silencing reduces β-catenin mRNA and protein levels in colorectal cancer cells." (PMID 27036017, 2016). "Subgroup analysis of p-STAT3 expression and clinicopathological feature of colorectal cancer." (PMID 27504822, 2016). "We questioned whether the STAT3 pathway is influenced by AF1q expression, because in colorectal cancer progression it was convincingly shown that both STAT3 and Wnt signaling are needed for full malignancy and cancer progression." (PMID 27259262, 2016). "The combined HR was 1.43 (95% CI: 1.23–1.67, P < 0.001, I2 = 0%) by random effects model, and when the fixed effects model was used, the same result was obtained, which revealed the positive correlation between p-STAT3 overexpression and poorer overall survival in colorectal cancer patients." (PMID 27504822, 2016). "Interestingly, knockdown of STAT3 significantly attenuated HDACIs-induced P-gp up-regulation in colorectal cancer cells, suggesting that STAT3 plays a crucial role in HDACIs-up-regulated P-gp." (PMID 27409663, 2016). "In addition to active STAT3 (p-STAT3), total STAT3 protein level was also increased in both high grade and low grade colorectal carcinomas." (PMID 27006530, 2016). "Xiong found that STAT3 down-regulated E-Cadherin expression via ZEB1 in colorectal cancer cells." (PMID 25947346, 2015). "Moreover, the STAT3/miR-34a/Snail axis promotes EMT-mediated colorectal cancer invasion and metastasis." (PMID 25638155, 2015). "The observed IL-11 expression and STAT3 activation in CD11b+ and/or CD14+ cell-infiltrating tumour sites of colorectal cancer patients strongly suggests that the induction of MDSCs may be mediated by IL-11-STAT3 signalling in the tumour microenvironment." (PMID 28781374, 2015).
colorectal cancer (continued). "Besides, inhibition of JAK1,2/STAT3 signaling induces apoptosis, cell cycle arrest, reduces tumor cell invasion in colorectal cancer cells." (PMID 26474284, 2015). "Finding the colorectal cancer cell growth-promoting activity of IL-6 agrees with the literature data, which additionally indicate that this cytokine exerts its effects via transsignaling, in particular involving the activation of STAT3." (PMID 26284488, 2015). "The most important signaling pathways regulating cell proliferation and survival implicated in colorectal cancer involve Wnt/β-catenin, phosphatidyl-inositol-3-kinase (PI3 K), growth factor receptors/Ras/mitogen-activated protein kinases (MAPK), JAKs/STAT3 and especially nuclear factor κB (NF-κB)." (PMID 26839513, 2015). "Moreover, GO-Y030 suppressed the growth of colorectal cancer stem cells by inhibiting phosphorylated STAT3 (pSTAT3), suggesting that curcumin analogs have anti-inflammatory activities such as those demonstrated with curcumin." (PMID 25331984, 2015). "In conclusion, siRNA targeting of B7-H4 effectively suppressed the proliferation, invasion, and migration of LOVO cells by inhibiting the effect of CXCL12/CXCR4 and the phosphorylation of JAK2/STAT3 on increasing the metastatic potential of colorectal carcinoma." (PMID 26078947, 2015). "Since miR-27a was reduced in human colorectal cancers, we determined whether p-STAT3 was increased in colorectal cancers." (PMID 25166914, 2014). "Conversely, Gordziel and colleagues found that strong STAT3 expression in colorectal carcinoma biopsies is associated with an improvement in median survival of about 30 months compared to STAT3 negative biopsies." (PMID 24518612, 2014). "Our results presented here show for the first time that GO-Y030 could efficiently inhibit STAT3 phosphorylation and cell viability, tumoursphere-forming capacity, and induce apoptosis in colorectal cancer stem cells." (PMID 21694723, 2011). "Interestingly, our results showed that the ALDH+/CD133+ subpopulations of SW480, HCT-116, DLD-1, and HT29 colorectal cancer cells expressed higher levels of STAT3 phosphorylation (Y705) compared with the ALDH−/CD133− subpopulation cells." (PMID 21694723, 2011). "Our results suggest that STAT3 is a novel therapeutic target in colorectal cancer stem cells, and the novel curcumin analogue, GO-Y030, might be used as a new therapeutic reagent to target colon cancer stem cells in future." (PMID 21694723, 2011). "Therefore, we demonstrated that colorectal cancer stem cells in the ALDH+/CD133+ cells expressed an activated form of STAT3, and this is the first report that demonstrates that these cancer stem cells are sensitive to GO-Y030 inhibition." (PMID 21694723, 2011). "Targeting STAT3 may be able to deplete the colorectal cancer stem cells and provide a promising approach to treat advanced colorectal cancer." (PMID 21694723, 2011). "Our results indicate that STAT3 is a novel therapeutic target in colon cancer stem cells, and inhibition of activated STAT3 in cancer stem cells by GO-Y030 may offer an effective treatment for colorectal cancer." (PMID 21694723, 2011). "Therefore, more potent analogues of curcumin that can inhibit the STAT3 pathway with lower doses are needed as a more efficient form of treatments for colorectal cancer." (PMID 21694723, 2011). "Our results also indicated that colorectal cancer-initiating cells or colon stem cells, characterised by the ALDH+/CD133+ subpopulations of colorectal cancer cells, expressed higher levels of STAT3 phosphorylation than the un-separated and ALDH−/CD133– subpopulations." (PMID 21694723, 2011).
colorectal cancer (continued). "It is postulated that elevated expression of STAT3 and its targeted genes in colorectal carcinoma may be one of malignancy markers." (PMID 22363883, 2011). "However, the constitutive activation of STAT3 is frequently detected in primary human cancer cells, including colorectal carcinoma cells." (PMID 21694723, 2011). "The constitutive activation of STAT3 is frequently detected in primary human colorectal carcinoma cells and established human colorectal cancer cell lines and elevated levels of STAT3 phosphorylation have been correlated with tumor invasion, nodal metastasis, and staging (P < 0.05)." (PMID 20712901, 2010). "Current studies have shown that piperine can inhibit colorectal cancer by regulating STAT3/Snail-mediated epithelial–mesenchymal transition (EMT), Nrf-2/Keap-1, and Wnt/β-catenin pathways, indicating that piperine may affect colorectal cancer through multiple signaling pathways." (PMID 38972051, 2025). "Yang P’s research demonstrated that LPS enhances PKM2 binding to the STAT3 promoter, which in turn promotes STAT3 transcription and nuclear translocation, leading to the secretion of pro-inflammatory cytokines and increased cell proliferation in colorectal cancer." (PMID 40057191, 2025). "Upregulation of DDLPS MDM2 by GP130 signal transduction may be facilitated by STAT1 and STAT3 transcription factors, as seen in colorectal cancer where GP130 activation by IL6 cytokine family member leukemia inhibitory factor led to increased MDM2 levels in a STAT3-dependent fashion." (PMID 40961077, 2025). "Notably, suppression of EGFR, SRC, STAT3, and AKT1, which are implicated in both inflammation and carcinogenesis, opens avenues for investigating BRLE in chemoprevention of colitis-associated colorectal cancer." (PMID 41465478, 2025). "Our current conjectures categorically suggest that PDIA3 might considerably modulate the M2 polarization within tumor-associated macrophages, thereby augmenting the tumorigenic capacity of colorectal cancer cells via manipulation of the STAT3/PD-1 signaling pathway." (PMID 38761176, 2024). "In addition, lncRNACASC2 could act as a ceRNA for miR-155, regulating the signal transducer and activator of transcription 3 (STAT3) expression and inhibiting the proliferative and metastatic capability of colorectal cancer cells." (PMID 39690146, 2024). "This, in turn, has an impact on the integrity of the intestinal barrier and the stability of the intestinal microenvironment, and that blocking the IL-6 -STAT3 signaling pathway through CN-encapsulated probiotics could prevent colitis-related colorectal cancer." (PMID 38717677, 2024). "Furthermore, RA acts as a considerably potent antitumor candidate against colitis-associated colorectal cancer by inhibiting toll-like receptor-4 (TLR4) and myeloid differentiation factor 2 (MD-2) complex-mediated nuclear factor-kappa B (NF-κB) and STAT3 activation." (PMID 39684626, 2024). "These revelations intimate that PDIA3 may contribute to the enhanced proliferation of colorectal cancer cells through its masterful orchestration of the STAT3/PD-1 signaling axis, thereby engendering an enriched environment for M2 macrophage polarization and protease secretion." (PMID 38761176, 2024). "Furthermore, the study suggests that the IL-6/STAT3 pathway enhances miR-92a expression by directly targeting its promoter, resulting in the activation of Wnt/β-catenin signaling and the subsequent promotion of stem-like traits in colorectal cancer cells." (PMID 38534736, 2024). "In addition, we used a STAT3 inhibitor to study succinate-driven STAT3 phosphorylation to affect tumor migration, and our results showed that when the colorectal cancer cell lines SW480 and HCT116 were treated with the STAT3 inhibitor HO-3867, the migration, invasion and EMT processes were weakened." (PMID 38486162, 2024).
colorectal cancer (continued). "Furthermore, the decreased infiltration of CD8+ T cells together with down-regulation of IL10 and up-regulation of IL17, STAT3 in the intestine, create an intestinal microenvironment prone to inflammation and the occurrence and development of colorectal cancer." (PMID 37143538, 2023). "Indeed, ANXA2 overexpression promotes colorectal cancer invasiveness through the STAT3 pathway and may regulate the proliferation, invasion and migration of colorectal cells through the same pathway." (PMID 36916296, 2023). "Moreover, previous studies revealed that the inhibition of PCSK9 might have an oncogenic role in the development and progression of colorectal cancer by inhibiting JAK2/STAT3 signaling." (PMID 37896137, 2023). "Additionally, HSP110 activates phosphorylation of STAT3 and promote colorectal cancer growth." (PMID 35986277, 2022). "KIF20A could promote the growth of colorectal cancer cells via the JAK/STAT3 signalling pathway." (PMID 36096734, 2022). "Moreover, persistent activation of STAT3 is implicated in IBD and colorectal cancer." (PMID 33633749, 2021). "In addition, a colorectal cancer study reported that miR-222/221 could activated NF-κB and signal transducer and activator of transcription-3 (STAT3)." (PMID 33391419, 2021). "Our findings demonstrate that bufalin suppresses tumour microenvironment-mediated angiogenesis by inhibiting the STAT3 signalling pathway in vascular endothelial cells, revealing that bufalin may be used as a new antiangiogenic adjuvant therapy medicine to treat colorectal cancer." (PMID 34496870, 2021). "Besides, PDCD4 knockout also promoted AOM plus DSS-induced colorectal cancer by the mechanism that PDCD4 deficiency increased the macrophage-secreted IL-6 induced by DSS and elevated the epithelial cell susceptibility to IL-6/STAT3 pathway-mediated cell proliferation during malignant transformation." (PMID 33099584, 2020). "These experimental results indicating that Ls inhibit the activation of downstream target genes may through inhibiting the activation of STAT3, which continue weakening its inhibitory effect on tumor cell apoptosis and further promoting the apoptosis of colorectal cancer cells." (PMID 31299960, 2019). "In addition, the result also showed that Ls could block the activation of STAT3 in human colorectal cancer HCT116 cells, which maybe the mechanism of Ls in anti-tumor effect." (PMID 31299960, 2019). "Indeed, analysis of a phase 3 clinical trial of BBI608 in patients with colorectal cancer was announced by Dr. D. J. Jonker at the “European Society for Medical Oncology 2016” and showed that STAT3 phosphorylation-positive patients exhibited significantly improved survival." (PMID 29849601, 2018). "Indeed, we have recently observed that IL-8 is overexpressed in a PTEN-loss context and downregulated in response to combined MAPK/PI3K inhibition in colorectal cancer models, possibly as a consequence of increased STAT3 phosphorylation (Ciuffreda, 2016, unpublished observation)." (PMID 28220839, 2017). "In addition, our results indicate IL-6/STAT3 pathway increases miR-92a expression by directly targeting its promoter, resulting in Wnt/β-catenin signaling activation and consequent promotion of stem-like phenotypes of colorectal cancer cells." (PMID 29254202, 2017). "Thus, it is necessary to investigate the relationship between p-STAT3 and colorectal cancer." (PMID 27504822, 2016). "The role of STAT1 and STAT3 for colorectal carcinoma (CRC) development and progression is controversial." (PMID 27191495, 2016). "Furthermore, inhibition of STAT3 reduced the ability of tumor-initiating colorectal carcinoma cells to form “tumor-spheres” in vitro, suggesting that STAT3 may be important for repopulation of tumors after treatment or for new metastases." (PMID 27584613, 2016).